CD4 (CD4 molecule)
Diseases named in the same sentence as CD4 in open-access papers (continued):
Sharing a sentence is not in itself a finding about the gene and the disease.
infection (continued). "Moreover, if differential immune responses were to play a significant role in the disparate infectability of the 2 groups of mice observed at 2 days after infection, one would expect to observe a shift in the CD4+/CD8+ cell ratios of the group that mounted an immune response." (PMID 33974566, 2021). "The decreased CD4+ T-cells proportion could promote infection and mortality in HD patients." (PMID 34356387, 2021). "Phenotypic tropism assays revealed that lentivirus reporters pseudotyped with 75 (80.6%) and 5 (5.4%) envelope clones could establish infection toward U87.CD4 cells expressing CCR5 (R5) and CXCR4 (X4), respectively; whereas the remaining 13 (14%) clones could infect both cells." (PMID 34305873, 2021). "We found a direct role of MSM-associated gut microbiomes overall and of Holdemanella specifically in driving CCR5 expression on CD4+ T cells, indicating that an MSM-microbiome induced increase in HIV co-receptor expression on CD4+ T cells may be one factor driving increased infection." (PMID 34818131, 2021). "However, in CM patients suffering from severe immunosuppression (CD4+ T cells <250 cells/μL), production of anti-cryptococcal IgG antibodies in response to infection may be impaired." (PMID 34367172, 2021). "Moreover, the efficiency of gp41-directed ACs was further improved via the addition of soluble CD4 and virtually eliminated p24 production in a mouse model of infection, compared to a gp120-directed carrier requiring 15-times higher dosage with marginal effect." (PMID 34276704, 2021). "SARS-CoV reactive CD4 + T cells could be detected even 17 years after infection." (PMID 34819019, 2021). "Although proinflammatory responses and the proximity of CCR5+ CD4 T cells (HIV target cells) to mucosal barriers are considered HIV-risk factors, when and how the immune system is regulated by the menstrual cycle to influence infection in the FRT remains undefined." (PMID 34229275, 2021). "As cell-to-cell contact is a hallmark of trans-infection, we next explored the possibility that the extent of HA “coating” on the fibroblast surface may dampen the ability of HIV to trans-infect from fibroblasts to CD4+ T cells." (PMID 33976386, 2021). "The detection of abundant viral RNA and/or mRNA in these animals indicates active infection with viral transcription and replication, although restricted viral replication without the production of infectious particles leading to pyroptosis in infected CD4 T-cells has been described for HIV." (PMID 34930327, 2021). "Thus, as suggested by others, infection through the FRT may depend on IFN-I signaling for CD4+ T cell recruitment and virus propagation." (PMID 34512664, 2021). "Interestingly, we observed approximately 6- to 9-fold higher viral production (day 2) for MDMs cocultured with WITO-infected CD4+ T cells than for MDMs cocultured with ADA-infected cells, despite the initially comparable infection of CD4+ T cells at the time of the coculture." (PMID 34425695, 2021). "However, virus that does end up captured via this route is protected from degradation by these more mature glycans, resulting in increased levels of CD4+ T cell transinfection and thus representing an additional viral route of infection free of bnAb interference." (PMID 33669676, 2021). "Thus, we inoculated cultures of 100 to 200 million primary, activated, rhesus CD4+ cells pooled from three naive Indian RMs at a multiplicity of infection (MOI) of approximately 0.01 with genetically homogeneous, sequence-confirmed, 293T transfection-derived virus stocks." (PMID 33658341, 2021). "The odds of beta/gamma HPV infection increased more than three times in HIV-infected MSM with a current CD4+ T-cell count <500 cells/mm3, suggesting that a poorer immunological status may favor the infection, either promoting its acquisition or delaying its clearance." (PMID 34202235, 2021).
infection (continued). "As a real infection is hardly comparable with vaccinations regarding induction of tissue-resident memory cells, further studies are necessary to elucidate how induction and reactivation of CD4+ Trm cells are regulated and which threshold exists to implement a sufficient memory response." (PMID 33595670, 2021). "Finally, although there was no category of CD4 count that was associated with having a persistent type-specific hrHPV infection, there was a marginally significant trend of WLWH in lower CD4 count categories being increasingly likely to have type-specific hrHPV persistence (ptrend = 0.06)." (PMID 33608036, 2021). "Consequently, sensing the infection through the so-called toll-like receptors (TRLs) would summon macrophages and dendritic cells (DCs) to the infection site, where they produce a Th1-type cytokine, IL-12, to more elicit T CD4+ and T CD8+ cells." (PMID 34692826, 2021). "However, CD8A+ cells also ubiquitously showed highest levels of CCL5 (RANTES), a chemokine previously shown to maintain CD4+ TRM cells after infection or sensitization, but that also attracts monocytes which were shown to promote the survival of MF cells in a mouse model." (PMID 33968070, 2021). "To determine whether the clonal burst size of Hulk-elicited 2W1S-specific CD4+ T cells could be increased following multiple infections, we also quantified 2W1S+CD4+ T cell expansion following three successive inoculations with 1,000 iL3 (schematic in S3A Fig)." (PMID 34237106, 2021). "HIV-1 induces a productive infection of T cells mainly by a process that involves the fusion of its envelope protein (gp120-gp41) to the plasma membrane, which is triggered by the interaction of gp120 with the CD4 molecule in collaboration with the HIV-1 co-receptors CXCR4 or CCR5." (PMID 33044676, 2021). "Higher IL-2 responses following vaccination may be due to shorter exposure to vaccine antigen compared with persistent antigen after infection, and consequent enhanced development of uncommitted IL-2+IFNγ- memory CD4+ T-cells, although this remains to be tested." (PMID 34960185, 2021). "The comparable levels of central memory CD4+ T-cells that we present here at three months post-infection/vaccination may not necessarily protect equally well against the development of severe disease following reinfection or break-through infection." (PMID 34960185, 2021). "We focused our work on the clearance of infected cells and utilized CD4+ T cells isolated from RMs at the peak of viremia (week 2 post infection), when the highest frequency of circulating infected cells expressed is expected and could be targeted for clearance." (PMID 34484212, 2021). "Interestingly, the ratio of CD4+ to CD8+ T cells was changed at an early stage of the infection." (PMID 34299148, 2021). "Moreover, infection with CRF55_01B was associated with a significantly faster increase of plasma HIV RNA load than infection with CRF01_AE and CRF07_BC, especially among the patients with initial CD4 count of 200–350 cells/μl." (PMID 34399785, 2021). "Together, these findings suggest that after vaccination, spike-specific CD4+ T cells in convalescent individuals may persist longer than those from infection-naïve individuals, but additional long-term follow-up studies will be required to directly test whether this indeed is the case." (PMID 34636722, 2021). "Thus, prevention strategies designed to block the infection of memory CD4+ T cells may prove effective in preventing HIV transmission." (PMID 34960667, 2021). "We therefore speculate that CGRP- and SAX-mediated inhibition of CD4+ T-cells infection with HIV-1, which we further observed ex-vivo, is mediated by CGRP and SAX acting on inner foreskin LCs and reducing their capacity to disseminate HIV-1 to CD4+ T-cells across cellular conjugates." (PMID 34956215, 2021).
infection (continued). "However, a higher level of PMN-MDSCs was observed in HIV patients with lower CD4+ T-cell counts during the acute phase of infection when compared to patients with high CD4+ T-cell counts, reflecting the importance of CD4+ T cells in shaping the clinical status." (PMID 34753323, 2021). "Similarly, the frequencies of specific central memory CD4+ T-cells and the proportions of central memory T-cells as a percentage of specific CD4+ T-cells were comparable after vaccination and infection (mean 0.045% ± 0.013 versus 0.033% ± 0.011 and mean 16% ± 2 versus 23% ± 6, respectively)." (PMID 34960185, 2021). "Thus, a complex pattern of antigen-specific activation of HLN CD4+ T cells in early infection may progress to T cell exhaustion in chronic infection." (PMID 34215335, 2021). "Furthermore, some memory cells may not secrete detectable levels of cytokines, especially the central compared to effector memory CD4+ population which develops at later time points after infection or vaccination." (PMID 34452002, 2021). "Interestingly, more than 70% and 50% of CD4+ Trm produced IL-17 in the WT/ΔPTX and WT/WT groups, respectively, highlighting the key contribution of this Trm population to producing a Th17 environment during infection." (PMID 34564636, 2021). "The adoptive transfer of CD25‐ CD4+ T cells to B cell–deficient and T cell–deficient mice (RAG‐deficient) resulted in an increase in liver pathology and mortality during S mansoni infection, suggesting an important regulatory role for Tregs during murine infection." (PMID 32692855, 2021). "Second, we investigated whether infection of and Co-IR expression in specific CD4 T-cell subsets as well as levels of cytokines that promote T-cell homeostasis prior to ART initiation predicted either suboptimal CD4 T-cell recovery or persistence of the HIV reservoir after ART." (PMID 34449812, 2021). "Therefore, we investigated whether DFV-B infection in EMT CD4+ T cells recapitulated the tendency of latency establishment." (PMID 33835029, 2021). "However, given the ubiquitous expression of this receptor on both innate and adaptive immune cells, IFNL has increasingly been shown to play a critical role in sculpting overall immune responses during infection and inflammation, promoting Th1 polarization of CD4+ T cells over Th2." (PMID 34899712, 2021). "Evidence also exists that the cytokine response of cross-reactive CD4+ T cells might be altered by the sequential infection with different DENV serotypes, leading to increased levels of pro-inflammatory cytokines that contributes to a detrimental immune response causing severe dengue." (PMID 33231723, 2021). "Previously, we found that genetic deletion of Sgl1 in the pathogenic fungus Cryptococcus neoformans (Cn) results in ergosterol 3β-D-glucoside accumulation, renders Cn non-pathogenic, and immunizes mice against secondary infections by wild-type Cn, even in condition of CD4+ T cell deficiency." (PMID 34620873, 2021). "Indeed, in humans, the degree of CD4 T cell differentiation is increased in people with active disease compared to latent tuberculosis infection (57, –, 59), indicating that progression of infection drives T cell differentiation." (PMID 33879592, 2021). "Consequently, we investigated whether pre-exposing virus to pEVs could impact the infection rate of CD4+ T cells." (PMID 34249000, 2021). "Since CD4 central memory T cells are not only long-lived, but also display exquisite proliferative capacities that can replenish the CD4 effector memory T-cell reservoir when stimulated, their infection might contribute to the slower decay in reservoir markers in people who delay ART initiation." (PMID 34841369, 2021). "In this study, we analysed the cellular response of hepatic lymph node cells and CD4+ T cells in terms of proliferative response, efficiency of antigen presentation and cytokine production, to F. hepatica-derived molecules, at early and late stages of the infection." (PMID 34215335, 2021).
infection (continued). "The number of IFN-γ+CD4+ T cells could effectively predict 30-day mortality of CRO infection." (PMID 33072617, 2020). "Similarly, in a study with mice infected with L. infantum, a high frequency of CD4+CD25+ T cells expressing FoxP3 was found in the lymph nodes in the first weeks of infection, followed by a decrease in the subsequent chronic phase of the disease, supporting the observed results in the present study." (PMID 32760744, 2020). "In the future, it is also important to investigate how CD4 T cell memory for each subset is formed and maintained and whether the plasticity of antigen cross-reactive CD4 T cell memory cells may shape the primary response to a new infection." (PMID 33126494, 2020). "Our data indicate that the lack of PD-L1 is associated with a lower production of IL-27 by monocytes infiltrating the lesion during the initial phase of infection, which might lead to a lower amount of CD4+Ly6Chi T effector cells and a diminished secretion of Th1 cytokines." (PMID 33193363, 2020). "Taken together, these findings indicate that antigen-unrelated CD4+ T cells can undergo bystander activation in the absence of TCR stimulation during infection, which could be implicated in both protective and pathogenic immune responses." (PMID 32859954, 2020). "These anatomical and subset characteristics of CD4+ T cells raise the question of whether bulk peripheral blood CD4+ T cell populations provide an accurate representation of the HIV-1 integration landscape throughout the body at multiple stages of infection." (PMID 32970634, 2020). "Therefore, we cannot rule out that host epigenetics may contribute to a reduction in detection of productive infection in less differentiated CD4+ T cell subsets in our assay." (PMID 32762760, 2020). "Moreover, by limiting immune activation very early after infection TGF-β1 may putatively reduce the availability of activated CD4+ cells to support HIV-1 replication and spread, although this has not been systematically investigated." (PMID 33329587, 2020). "In contrast, people treated for more than 12 months with an estimated 12-month change in CD4 count before LTFU above than 50 cells/μL, who had a higher rate of re-engagement in care, may have had a well-controlled infection due to a better adherence to ART allowing increase in CD4 count." (PMID 32911516, 2020). "Another study by Antunes et al37 revealed similar results and demonstrated that transferring CD4+CD25+CD127dim Tregs to Rag‐1−/− mice infected by influenza A virus, that causes injury to the respiratory organs, led to significant delay in extended survival time after infection." (PMID 32838397, 2020). "On the other hand, the functional nature of these CD4+ or CD8+ T-cell subsets upon infection with HIV could be predicted from the expression of several negative immune checkpoint molecules, for instance PD-1, TIM3, LAG3, and CD160, which all correlate with HIV viral load in the host." (PMID 32876566, 2020). "Adaptative immunity relies on the migration of antigen presenting cells (APCs) from the site of infection to secondary lymphoid organs and the activation of resident APCs through exposition to T. gondii antigens and on their ability to present antigens and to activate B cells, CD4+ and CD8+ T cells." (PMID 33324583, 2020). "Studies on cross-reactivity of CD4+ T cells specific for mosquito-borne flaviviruses indicate that e.g., JEV-specific CD4+ T cells can recognize other flaviviruses which may result in stronger CD4+ T cell responses upon secondary infection with a heterologous virus." (PMID 32806696, 2020). "Moreover, a role for Th17 cells cannot be excluded, however we were not able to detect IL-17 production by CD4+ T cells in the context of Il27ra-deficiency in this infection model." (PMID 33049000, 2020).
infection (continued). "We tested whether modelled reductions in total new HIV diagnoses, diagnoses with acute infection, diagnoses with early infection(CD4 > 500 cells/μl), diagnoses adjusted for testing volume, or the proportion virally non-suppressed, reflected HIV incidence reductions." (PMID 33285419, 2020). "Second, while 10 days post infection was an adequate time point in a previous Cs/Ct challenge study, 24 dpv (thus, 10 days post boost vaccination) might have been too late for the detection of vaccine-induced CD4 IFN-γ production." (PMID 32630694, 2020). "Furthermore, the expansion of CD4+ FoxP3+ T cells in lymphoid organs of mice with chronic T. canis infection, along with the higher levels of IL-10 in spleen and sera, support their role in the host systemic regulatory response to the infection." (PMID 32268573, 2020). "While CD4+ T cell polarization and formation of a memory population is less clear during human C. trachomatis infection, there is evidence to suggest that both Th1 and Th2 populations are present and may protect against subsequent infections." (PMID 33091023, 2020). "Furthermore, other naturally occurring polymorphisms within Tat identified in HIV-infected patients at acute and/or early infection phase (i.e., P10S, W11R, K19R, A42V, and Y47H) have been shown to significantly impair transactivation activity in the infected CD4+ T lymphocytes." (PMID 33383617, 2020). "Indeed, endosomal TLR agonists' administration during chronic stages of infection may lead to CD4 T cell death and/or exacerbate hypergammaglobulinemia." (PMID 32547564, 2020). "In the present study, lack of correlations between miR16-5p, miR26a-5p and miR-150 levels and the CD4+ cell count may be due to a number of factors, including ART resistance, long infection times (∼10 years) and different types of immunological damage (high viral loads and low CD4+ cells counts)." (PMID 32319513, 2020). "This could e.g. include antibodies blocking ESAT-6-mediated virulence or variations in local antigen concentration/positioning during infection, where effector CD4 T cells would need to recognize Mtb infected cells instead of bystander cells presenting soluble secreted antigens." (PMID 33240275, 2020). "The percentages of splenic Th1, Th2, and Treg in CD4+T cells were significantly increased in both 2 and 8 weeks PI of C. sinensis, while the ratio of Treg/Th17 as well as the percentage of Treg in serum was gradually increased during the development of infection." (PMID 33489026, 2020). "In our system, an increase in the proportion of CD4+ T cells in spleen cells and the parallel elevation of IL-2, IFN-γ, and TNF-α in serum after 11 days of infection in mice suggested that Th1 immune responses may be caused by early infection by T. pallidum." (PMID 33488577, 2020). "CD4+ T cell subsets that express more CCR5 were more susceptible to infection with C-HIV Envs, suggesting that these may be the major cellular targets during the first 3 years of infection." (PMID 32762760, 2020). "Similarly as in the lungs, the CD8+ and CD4+ T cells became activated in the spleen upon infection, as was shown by an increased proportion of Teff cells and a decreased proportion of Tnaive cells compared to the uninfected controls, without any change during resolution." (PMID 33664739, 2020). "Importantly, we identify a small-molecule inhibitor that can be used to block type I IFN signaling during established infection and acts synergistically with conventional anti-parasitic drugs to improve parasite clearance and enhance anti-parasitic CD4+ T cell responses in mice and humans." (PMID 32101732, 2020). "Thus, changes within the CD4 T cell compartment during numerical recovery impact their ability to respond to newly encountered Ags, which likely impacts their ability to provide protection against newly encountered infections." (PMID 32733454, 2020).